DPP4 (dipeptidyl peptidase 4)
Diseases named in the same sentence as DPP4 in open-access papers (continued):
Sharing a sentence is not in itself a finding about the gene and the disease.
kidney cancer (2 papers, 2020 to 2023). Primary or metastatic malignant neoplasm involving the kidney. "This is why it is not unexpected to notice the encouraging findings about metformin sensitivity to distinct kidney cancer cell lines with the association of DPP4 expression by utilizing DepMap." (PMID 37624423, 2023).
left ventricular hypertrophy (2 papers, 2020 to 2025). Enlargement of the LEFT VENTRICLE of the heart. "DPP4−/− markedly reduced the ratio of HW/TL in stressed mice, suggesting that DPP4−/− improved left ventricular hypertrophy." (PMID 39968759, 2025).
lower respiratory tract infection (2 papers, 2019 to 2020). "MRRS-CoV uses dipeptidyl peptidase 4 (DPP4) as a receptor to enter the host cell and causes lower respiratory tract infection and damage to the innate and adaptive immune system, resulting in a cytokine storm." (PMID 32640525, 2020). "Rabbits developed both upper and lower respiratory tract infection upon MERS-CoV inoculation, either via intranasal or combined intranasal and intratracheal routes, in line with the localization of DPP4 in their respiratory tract epithelium." (PMID 31022948, 2019).
lymph node metastasis (2 papers, 2015 to 2022). "The expression of DPP4 in the group with lymph node metastasis was higher than that in the group without lymph node metastasis, N0 vs. N1 (p < 0.05)." (PMID 36467461, 2022).
myotonic dystrophy type 1 (2 papers, 2024 to 2025). Steinert disease, also known as myotonic dystrophy type 1, is a muscle disease characterized by myotonia and by multiorgan damage that combines various degrees of muscle weakness, arrhythmia and/or cardiac conduction disorders, cataract, endocrine damage, sleep disorders and baldness. "Although these findings have not yet been validated in patients with type 1 myotonic dystrophy (DM1), they provide new avenues for exploring whether DPP-4 inhibitors could improve muscle function or slow the progression of fibrosis in DM1 patients." (PMID 41018201, 2025).
nasopharyngeal carcinoma (2 papers, 2023 to 2025). A carcinoma arising from the nasopharyngeal epithelium. "Further basic research should be conducted using DPP4 inhibitors and nasopharyngeal cancer cell lines." (PMID 37185411, 2023). "A multivariate analysis revealed that oral hypoglycemic agents such as AGI and DPP4 inhibitors reduce nasopharyngeal cancer mortality." (PMID 37185411, 2023). "One study reported that while SGLT‐2 inhibitors were linked to a significantly lower risk of nasopharyngeal carcinoma (NPC) than other anti‐diabetic drug dipeptidyl peptidase 4 (DPP‐4) inhibitors, their association with overall HNC was not statistically significant." (PMID 40387523, 2025). "Thus, the DPP-4 inhibitor can be an effective regimen for suppressing nasopharyngeal cancer cells." (PMID 37185411, 2023).
nephritis (2 papers, 2020 to 2025). Inflammation of renal tissue. "Certain associations, like statins with myositis, PPIs/NSAIDs with nephritis, and DPP4 inhibitors with bullous skin disorders, also occur outside the ICI setting." (PMID 40521636, 2025).
nephrosclerosis (2 papers, 2015 to 2020). Hardening of the kidney due to infiltration by fibrous connective tissue (fibrosis), usually caused by renovascular diseases or chronic hypertension. "Non-immune glomerular diseases including minor glomerular abnormality and nephrosclerosis showed no clear DPP-4 active lesion in glomerular resident cells." (PMID 32948146, 2020).
pancreatic disease (2 papers, 2016 to 2022). "DPP-4 inhibitors and GLP-1 receptor agonists have been associated with adverse outcomes, including pancreatic disorders, although some of these findings are controversial." (PMID 26989609, 2016).
periodontal disease (2 papers, 2024 to 2025). "It is possible that P. gingivalis, a keystone pathogen that has been linked to the pathophysiology of periodontal disease, and host tissues are the main sources of DPP-4 in saliva." (PMID 38337597, 2024). "In GCF, DPP-4 levels are expected to be greater during disease activity, as both of these sources are expected to increase as the disease progresses, which may lead to its association with the advancement of periodontal disease." (PMID 40429343, 2025). "Periodontal disease-related bone and connective tissue damage could be attributed to human DPP-4 and the DPP-4-like enzyme of P. gingivalis." (PMID 40429343, 2025). "Additionally, it has been demonstrated that P. gingivalis DPP-4 increases the activity of host-derived matrix metalloproteinases (MMP)-1 (collagenase) and -2 (gelatinase), which are hypothesized to be implicated in the breakdown of connective tissue in periodontal disease." (PMID 40429343, 2025).
primary immunodeficiency (2 papers, 2023 to 2025). "Both TXN and DPP4 were found to be enriched in several shared pathways, including spliceosome, antigen processing and presentation, primary immunodeficiency, and regulation of autophagy." (PMID 40124361, 2025). "DPP4 and NR1D1 were associated with primary immunodeficiency, along with the T cell receptor signaling pathway." (PMID 37928394, 2023).
prostate (2 papers, 2021 to 2024). "Because DPP4 inhibitors are typically used as second or third-line agents for glycemic control in type two diabetes, a small sample size of diabetic patients on DPP4 inhibitors who had advanced-stage prostate were identified." (PMID 34055551, 2021).
Respiratory tract infection (2 papers, 2018 to 2023). An infection of the upper or lower respiratory tract. "In sensitivity analysis findings remained consistent with the primary analysis showing no significant increased or decreased risk of respiratory tract infections among users of DPP-4 inhibitors." (PMID 30310100, 2018). "The underlying mechanisms have not been fully elucidated, but speculation has arisen over DPP-4 inhibitors’ potential effects on diabetic patients’ immune responses, which could debilitate patients’ immune response to respiratory tract infections, sepsis and other severe infections." (PMID 37891260, 2023).
retinal edema (2 papers, 2021 to 2025). "In a 2020 experimental study, the results revealed that prolonged DPP4 inhibition destabilized the blood-retina barrier, potentially inducing retinal edema." (PMID 34203446, 2021). "However, an experiment revealed that long-term inhibition of DPP-4 destabilized the blood–retina barrier, potentially leading to retinal edema." (PMID 40308768, 2025).
scoliosis (2 papers, 2022 to 2025). A congenital or acquired spinal deformity characterized by lateral curvature of the spine. "Based on above results, lower DPP-4 was associated with abnormal metabolism of musculoskeletal system in AIS, thus disturbing the homeostasis of spine and making adolescent more susceptible to scoliosis." (PMID 35139864, 2022).
ST Elevation Myocardial Infarction (2 papers, 2017 to 2025). A myocardial infarction that produces elevation in the ST segments of the ECG. "Furthermore, high levels of DPP4 have been associated with future major adverse cardiovascular events in diabetic patients with ST elevation myocardial infarction." (PMID 41141478, 2025).
Thromboembolism (2 papers, 2021 to 2023). The formation of a blood clot inside a blood vessel that subsequently travels through the blood stream from the site where it formed to another location in the body, generally leading to vascular occlusion at the distant site. "The DPP4 inhibitor use was found to be a significant predictor of thromboembolism during hospitalization, with an adjusted OR of 2.249 (95% CI: 1.073–4.713) and a p-value of 0.032." (PMID 37374918, 2023).
thyroid tumor (2 papers, 2021 to 2024). A benign or malignant neoplasm affecting the thyroid gland. "Similarly, previous studies have shown that DPP4 silencing or treatment with sitagliptin significantly reduced thyroid tumour growth in vivo." (PMID 33513866, 2021).
type 2 diabetic nephropathy (2 papers, 2011 to 2017). "Twenty-five patients with type 2 diabetic nephropathy received anagliptin 200 mg/day for 24 weeks, and 20 patients who were switched to anagliptin from other dipeptidyl peptidase-4 (DPP-4) inhibitors were analyzed regarding primary and secondary endpoints." (PMID 28761658, 2017). "This study was performed to assess the effect of chronic low-dose sitagliptin, a dipeptidyl peptidase 4 inhibitor, on metabolic profile and on renal lesions aggravation in a rat model of type-2 diabetic nephropathy, the Zucker diabetic fatty (ZDF) rat." (PMID 22203828, 2011).
uveitis (2 papers, 2022 to 2026). An inflammatory process affecting a part of or the entire uvea. "Urinary proteomic profiling in BD-associated uveitis has identified differentially expressed proteins such as CD38, dipeptidyl peptidase-4 (DPP4), creatine kinase B-type, and S100A8/A9, suggesting potential relevance for monitoring ocular inflammation." (PMID 41596381, 2026).
venous thromboembolism (2 papers, 2023 to 2025). Occlusion of the lumen of a vein by a thrombus that has migrated from a distal site via the blood stream. "In addition, DPP4 inhibitors may cause infectious diseases, thereby greatly increasing the risk of venous thromboembolism." (PMID 36769291, 2023).
Ventricular arrhythmia (2 papers, 2015 to 2020). "Taken together, regardless of the relative importance of each of these factors (reduced ROS generation, increased ATP resynthesis, and vasodilatation), all of the DPP-4 inhibitor-caused changes are compatible with our understanding of their protective effects against ventricular arrhythmias." (PMID 25388908, 2015).
abscesses (1 paper, 2024). "Compared to mice challenged with a DPP-4-deficient strain, mice injected with the P. gingivalis W83 strain were seen to pass away and to develop abscesses more frequently." (PMID 38337597, 2024). "Additionally, using a mouse subcutaneous abscess model, it was showed that DPP4 was related directly to biofilm development." (PMID 38337597, 2024).
airway hyperresponsiveness (1 paper, 2013). "In contrast, aerosolization of the DPP4 inhibitor simultaneously with the allergen significantly reduced airway hyperresponsiveness and ameliorated histopathological signs compared to controls." (PMID 24303167, 2013).
allergic rhinitis (1 paper, 2019). Inflammation of the nasal mucous membranes caused by an IgE-mediated response to external allergens. "DPP-4 inhibitor users had a reduced risk of allergic rhinitis (aHR = 0.74, 95% confidence interval (CI) = 0.61–0.90) in all stratifications." (PMID 31013793, 2019). "Among women, DPP-4 inhibitor users had a lower risk of allergic rhinitis (aHR = 0.67, 95% CI = 0.50–0.90)." (PMID 31013793, 2019). "High-dose (cumulative defined daily dose ≧648mg) DPP-4 inhibitor users had a decreased risk of allergic rhinitis (aHR = 0.23, 95% CI = 0.15–0.35)." (PMID 31013793, 2019). "Among patients with comorbidities, the risk of allergic rhinitis for DPP-4 inhibitor users was 0.73 (95% CI = 0.60–0.90)." (PMID 31013793, 2019).
Alopecia universalis (1 paper, 2021). Alopecia universalis is the most severe form of alopecia areata, an inflammatory disease of the hair follicle, which is characterized by a complete loss of hair of the scalp and all the hair-bearing areas of the body. "A 64-year old man developed alopecia universalis after one month of treatment with metformin and sitagliptin, a dipeptidyl peptidase‐4 (DPP-4) inhibitor." (PMID 33205256, 2021). "Ein 64-jähriger Patient entwickelte 1 Monat nach Therapieeinleitung mit Sitagliptin, einem Dipeptidylpeptidase-4(DPP‐4)-Inhibitor, und Metformin eine Alopecia universalis." (PMID 33205256, 2021).
anal carcinoma (1 paper, 2024). "DPP4 was associated with a lower risk of anal carcinoma in both two-sample MR analyses and SMR analyses." (PMID 38504335, 2024). "The SMR analyses uncovered the genetic connections of anal carcinoma risk with ABCC8 (OR = 1.762; 95% CI: 1.034–3.022; P-value = 0.037) and DPP4 (OR = 0.100; 95% CI: 0.011–0.893; P-value = 0.039)." (PMID 38504335, 2024). "Strong evidence suggested colocalization between DPP4, GLP1R, ABCC8/KCNJ11, and anal carcinoma." (PMID 38504335, 2024).
Arterial thrombosis (1 paper, 2020). The formation of a blood clot inside an artery. "To address this knowledge gap, we examined whether inhibition of DPP-4 can inhibit platelet activation and arterial thrombosis by preventing platelet mitochondrial dysfunction and release." (PMID 33328991, 2020).
Ataxia (1 paper, 2023). Ataxia refers to impaired coordination of voluntary muscle movement. "Inhibition of Dpp4 showed a neuroprotection effect in diabetic mouse brain, and the Cacna2d2 mutant mice were affected with cerebellar neuro-degeneration associated with ataxia and seizures." (PMID 36831877, 2023).
atrial flutter (1 paper, 2025). A disorder characterized by an electrocardiographic finding of an organized, regular atrial rhythm with atrial rate of 240-340 beats per minute. "Moving to more novel antidiabetic agents, a metanalysis of six clinical trials with 5250 DM patients showed that dipeptidyl peptidase-4 (DPP-4) inhibitors did not have any significant impact on AF risk, and in fact, increased the risk of atrial flutter." (PMID 40729028, 2025).
autoimmune thyroiditis (1 paper, 2024). "Finally, we did not investigate the effects of DPP4 inhibitors in the experimental autoimmune thyroiditis (EAT) mice model." (PMID 38127960, 2024).
balanitis (1 paper, 2023). An infectious or non-infectious inflammatory process that affects the glans penis. "In an initial analysis, the occurrence of genital candida infections (vaginitis and vulvovaginitis in women; balanitis, balanoposthitis, phimosis, and paraphimosis in men) in those taking SGLT2i vs. DPP4-i was evaluated." (PMID 37175805, 2023).
biliary atresia (1 paper, 2025). A rare, biliary tract disease characterized by progressive obliterative cholangiopathy of the intra- and extrahepatic bile ducts, occurring in the embryonic/ perinatal period, leading to severe and persistent neonatal jaundice and acholic stool. "Our findings of increased serum DPP4 activity in both experimental and human biliary atresia (BA) align with previous reports demonstrating elevated DPP4 activity in the urine and serum of infants with BA45,46." (PMID 40825831, 2025).
bladder tumors (1 paper, 2024). "In BCa, upregulation of DPP4 is correlated with aggressive and advanced-stage bladder tumors and the knockdown of DPP4 decreases the survival, proliferation, migration, and invasion of BCa cell lines." (PMID 39409924, 2024).
calcification (1 paper, 2021). Process by which organic tissue becomes hardened by the physiologic deposit of calcium salts. "As evogliptin, one of the DPP-4 inhibitors displays high specific accumulation in cardiac tissue, we here evaluated its therapeutic potency for attenuating valvular calcification in CAVD animal models." (PMID 33401457, 2021).
carcinomas in situ (1 paper, 2025). "Among all cell clusters from both carcinomas in situ and lung metastases, tumor cells were most sensitive to paclitaxel, with DPP4 expression being reduced by more than half." (PMID 40708008, 2025).
cardioembolic stroke (1 paper, 2019). "Another real world data from the Taiwan National Health Insurance Database showed that treatment with dipeptidyl peptidase-4 inhibitor was associated with a lower risk of new-onset atrial fibrillation which is the most common cause of cardioembolic stroke." (PMID 31151454, 2019).
carotid artery thrombosis (1 paper, 2020). Blood clot formation in any part of the carotid arteries. "A limitation of experiments using the carotid artery thrombosis model is that the prothrombotic effects of platelet-derived DPP-4 cannot be definitively proven to be caused by thrombin generation." (PMID 33328991, 2020).
Chronic colitis (1 paper, 2025). A chronic inflammatory disease of the large intestine (colon, cecum and rectum). "Similarly, in a DSS-induced chronic colitis model, fibrosis formation was accompanied by increased DPP4 protein expression." (PMID 41334589, 2025). "To extend our mechanistic insights to clinical relevance, we evaluated the efficacy of Dau-d4, a selective inhibitor of microbiota-derived DPP4, in a DSS-induced chronic colitis model." (PMID 41334589, 2025). "To further assess the contribution of bacterial and host-derived DPP4 to intestinal fibrosis in CD, and to evaluate the therapeutic potential of targeting both sources of DPP4, we conducted in vivo experiments using the DSS-induced chronic colitis model." (PMID 41334589, 2025).
collagenous colitis (1 paper, 2022). A type of microscopic colitis of unknown etiology. "Drug‐induced collagenous colitis (non‐steroidal anti‐inflammatory drugs, proton pump inhibitors, angiotensin receptor antagonists), ursodeoxycholic acid, lactulose, antibiotics, DPP4 inhibitors, immune checkpoint inhibitors, and so forth." (PMID 35310743, 2022).
colorectal adenocarcinoma (1 paper, 2021). The most common type of colorectal carcinoma. "Tylonycteris-bat-CoV-HKU4 replicates efficiently in human colorectal adenocarcinoma and hepatocarcinoma cells with cytopathic effects, and can utilize human-dipeptidyl-peptidase-4 and dromedary camel-dipeptidyl-peptidase-4 as the receptors for cell entry." (PMID 33431849, 2021).
corneal disorder (1 paper, 2024). A non-neoplastic or neoplastic disorder that affects the cornea. "On the other hand, the sex, T2DM-related complications and T2DM medications including DPP4 inhibitors and insulin did not alter the correlation between SGLT2 inhibitors application and the development of corneal diseases." (PMID 38322591, 2024). "Besides, the T2DM duration and T2DM medications that could reflect the glycemic levels such as DPP4 inhibitors and insulin did not alter the effect of SGLT2 inhibitors on corneal diseases development, which further support the universal protective effect of SGLT2 inhibitors on corneal disorders." (PMID 38322591, 2024).
coronary atherosclerosis (1 paper, 2025). Atherosclerosis of the coronary vasculature. "DPP-4 inhibitors significantly reduced the development of coronary atherosclerosis in type 2 diabetic patients in clinical trials." (PMID 40429343, 2025).
diastolic heart failure (1 paper, 2015). Heart failure caused by abnormal myocardial relaxation during diastole leading to defective cardiac filling. "One study focused on diastolic heart failure and only found a weak correlation with DPP4 activity in peripheral venous plasma, while a second study only included patients with a Left Ventricular Ejection Fraction lower than 45%." (PMID 26544044, 2015).
ductal carcinoma (1 paper, 2022). "Since TNBC and ductal carcinoma are not identical, ductal carcinoma tissue sections cannot fully represent TNBC data, which might be the reason for the absence of DPP4 protein staining in the sections." (PMID 36568247, 2022).
eosinophilia (1 paper, 2025). "Biomarkers like DPP-4 have emerged as endotype-specific markers, with data from the ProRaD cohort linking them to clinical features such as keratosis pilaris, perleche, and eosinophilia, highlighting the systemic impact of inflammation even in milder disease (EASI < 16)." (PMID 40141720, 2025).
Ewing Sarcoma Family of Tumor (1 paper, 2023). "In Ewing Sarcoma Family of Tumor (ESFT) cells, the knockdown of DPP4, DPP8, or DPP9 leads to NPY-mediated apoptosis." (PMID 37626841, 2023).
experimental arthritis (1 paper, 2018). ARTHRITIS that is induced in experimental animals. "In addition, DPP4 was negatively associated with inflammation in terms of proinflammatory chemokines such as stromal cell-derived factor-1, which is involved in human and experimental arthritis." (PMID 29556215, 2018).
gastric diseases (1 paper, 2024). "However, the current literature surrounding novel anti-diabetic agents such as sodium-glucose cotransporter 2 inhibitors (SGLT2I) and dipeptidyl peptidase 4 inhibitors (DPP4I) on various gastric diseases remain controversial." (PMID 38856768, 2024).